IL6 (interleukin 6)
Diseases named in the same sentence as IL6 in open-access papers (continued):
Sharing a sentence is not in itself a finding about the gene and the disease.
COVID-19 (continued). "The pathophysiological mechanism of C3a/C5a in COVID-19 remains ambiguous, but these complement anaphylatoxins are known to stimulate inflammatory cytokine (notably IL-6 and TNF) release from macrophages and other cells expressing C3a/C5a receptors." (PMID 33375371, 2020). "Tocilizumab, a monoclonal antibody against interleukin-6, has shown some efficacy in the treatment of severe COVID-19, although the significant cost of this product can be a limiting factor in its widespread use." (PMID 33133323, 2020). "Ten (5.2%) physicians noted other markers as determinants of COVID-19 outcome, namely interleukin-6 (IL-6), LDH, transaminase, creatine-phospho-kinase (CPK), and procalcitonin." (PMID 32748880, 2020). "According to a report by Yong Gao, the levels of IL-6 and d-dimer can be measured to estimate the severity of COVID-19 and help to diagnose severe COVID-19 patients earlier." (PMID 33520906, 2020). "The main player in this cytokine storm, incriminated in COVID-19 as well, is interleukin-6 (IL-6), which is secreted by innate immune cells and monocytes and is also a fine-tuning regulator of CD4+, CD8+ T cells, and B cells and activates monocytes." (PMID 32471171, 2020). "Evidence has shown that IL-6 levels in COVID-19 patients needing critical care continues to increase over time and are relatively more elevated in nonsurvivors than in survivors." (PMID 33584679, 2020). "Previous studies showed that the serum IL-6 level in patients with COVID-19 is increased, and its circulating level is positively correlated with the severity of the disease." (PMID 33132913, 2020). "The association of biomarkers of coagulation and myocardial function with outcome reflects the multifactorial pathogenesis of COVID-19, and its potential reversibility with anti-IL-6 therapy before the overt disease is manifested." (PMID 33033405, 2020). "Systemic inflammation in COVID-19 patients is a participant effector that magnifies vascular pathology, as it includes the pro-coagulant mediators IL-6 plus IL-6R, which induce the vascular-permeability effector VEGFA." (PMID 32629875, 2020). "The TNF-α and IL-6 levels in the peripheral blood of COVID-19 patients in the general, severe and critical groups were significantly higher than those in peripheral blood of the subjects in the normal control group." (PMID 32976531, 2020). "Several studies have suggested a link between high IL-6 levels and disease severity in COVID-19, indicating that IL- 6 is involved in down-regulation of HLA-DR and lymphopenia, contributing to the sustained cytokine levels seen in severe COVID-1911,15." (PMID 33303843, 2020). "The most notable factor was IL6, which plays a key role in the cytokine storm, and is used as a clinical early warning index in the diagnosis and treatment of COVID-19." (PMID 32754224, 2020). "At present, anti-IL-6, antiviral therapy, convalescent plasma, hydroxychloroquine, and azithromycin among others are being investigated as potential treatments for COVID-19." (PMID 32405877, 2020). "For this reason, ongoing trials are addressing the combined use of IL-6 antagonists and antifungal prophylaxis in severe COVID-19 patients." (PMID 32599813, 2020). "We present here a case of a 55-year-old male COVID-19 patient with an unusual high level of interleukin 6 (IL-6)." (PMID 33304877, 2020). "Conclusively, increase of peripheral blood IL-6 and decrease of lymphocytes can be used as the indicators of severe COVID-19." (PMID 33329518, 2020). "Low HLA-DR expression was recently shown to be associated with monocyte hyperactivation and excessive release of interleukin-6 (IL-6) in COVID-19 patients." (PMID 33377122, 2020). "The uncontrolled production of IL-6 has been demonstrated to correlate with disease progression and severity, predicting respiratory failure in hospitalized symptomatic COVID-19 patients." (PMID 33312199, 2020).
COVID-19 (continued). "COVID-19, like other CoV infections, causes ALI with high viral titers, high levels of the inflammatory cytokines IL-1β and IL-6 as well as infiltration of macrophages and neutrophils into the lungs." (PMID 33149733, 2020). "The expression of IL-6, which plays an important role in the pathogenesis of COVID-19, is increased by TNF." (PMID 33329059, 2020). "Lymphopenia and the levels of IL-6, IL-10, and TNF-α were found to be negatively associated with COVID-19 patient survival." (PMID 32967229, 2020). "Due to lack of sufficient information about the expression levels of Tregs and its role in regulation of IL-6 cascade in COVID-19 patients, this study aimed to evaluate the expression level of IL-6 and CD4+ Foxp3+ CD25+T cells in COVID-19 patients." (PMID 33244382, 2020). "SARS-CoV-2 infection can induce a cytokine storm characterized by upregulation of IL-6 and IL-1, etc., and this observation constitutes the rationale of anti-IL-6 and anti-IL-1 therapeutics in COVID-19 patients." (PMID 33142844, 2020). "And, in the Chinese Clinical Guidance for COVID-19 Pneumonia Diagnosis and Treatment (7th Edition), published by China National Health Commission on March 4, 2020, IL-6 is the part of measurements." (PMID 33024459, 2020). "By contrast, individuals with COVID-19 who experience more mild disease have lower levels of IL-6, together with activated T lymphocytes and IgM SARS-CoV-2-binding antibodies." (PMID 32655582, 2020). "The anti-IL-6R antibodies tocilizumab and sarilumab and the anti-IL-6 antibody siltuximab are currently being tested in 13 clinical trials for efficacy in managing COVID-19 CSS and pneumonia." (PMID 32849908, 2020). "Insight into the inflammatory profiles shows that IFN-γ, together with IL-6 and IL-10, increased in patients with a severe type of COVID-19 compared to those with a mild type." (PMID 33133104, 2020). "IL-1 and IL-6 are likely involved in the development of fever, which is the most common COVID-19 symptom." (PMID 33072624, 2020). "Cytokine storm during SARS-CoV-2 infection is a possible mechanism of morbidity and mortality, and IL-6 is one of the major inflammatory molecules involved in COVID-19." (PMID 33284859, 2020). "Conclusively, the increase of serum IL-6, decrease of lymphocytes and increase of neutrophils should be also paid attention in older patients infected of COVID-19." (PMID 33329518, 2020). "Other IL-6 inhibitors, such as siltuximab and sarilumab, have been reported as salvage therapy for COVID-19." (PMID 33364959, 2020). "The strongest predictors of in-hospital mortality in COVID-19 patients include elevated interleukin -6 (IL-6) and D-dimer levels at hospital admission." (PMID 33542685, 2020). "The therapeutic potential of blockade of IL-6 signaling for COVID-19 is reviewed in more detail in other review articles in this series." (PMID 32834892, 2020). "With increasing research on severe COVID-19, T lymphocytes, lactic acid, and interleukin-6 (IL-6) have been identified to be helpful in the early identification of severe disease." (PMID 32766268, 2020). "Instead, we tested the predictive power of age, gender and BMI on COVID-19-related complications, but apart from plasma IL6 levels and stimulated IFNγ levels the other variables remained non-significant at multivariable analysis." (PMID 33585507, 2020). "In fact, elevated levels of IL-6 were found to be a stable indicator of poor outcome in patients with severe COVID-19 with pneumonia and ARDS." (PMID 32690985, 2020). "Such a crucial role of IL-6 provided the rational basis for considering anti-IL-6 monoclonal antibodies (i.e. tocilizumab) as promising drugs for COVID-19." (PMID 32765279, 2020). "Studies have shown that the expression levels of serum IL-2R, IL-6, and other cytokines in patients with COVID-19 dramatically increased on average, particularly in the critical patients." (PMID 33042873, 2020).
COVID-19 (continued). "Although its complex pathophysiology is beyond the scope of this mini-review, the relationship to thrombosis of one of the main factors involved, IL-6, found in very high levels in COVID-19 patients must be acknowledged." (PMID 33488398, 2020). "COVID-19 patients with moderate-to-high levels of IL-6 show an elevation in creatine, creatinine, polyamines spermidine and acetyl-spermidine." (PMID 33495710, 2020). "Consistent with this notion, plasma levels of CCL-2 and IP-10 were elevated earlier than IL-6 in intensive care unit (ICU) COVID-19 patients." (PMID 32766256, 2020). "For example, a strong upregulation of the proinflammatory cytokines TNF-α, IL-1β, and IL-6 was found in patients presenting severe forms of COVID-19 compared to patients with milder forms." (PMID 33362557, 2020). "Evaluating the expression level of CD4+ FoxP3+ CD25+ T cells and IL-6 in peripheral blood samples of hospitalized COVID-19 patients." (PMID 33244382, 2020). "The strong positive correlation between circulating IL-6 levels and illness severity in hospitalized COVID-19 patients provides the rationale for deployment of IL-6R inhibitors in a selection of infected patients." (PMID 33584679, 2020). "The cytokine serum levels, specially IL-2R and IL-6 in patients with COVID-19, positively correlate with mortality rate." (PMID 33041985, 2020). "Interleukin-6 (IL-6) plays a vital role in inducing cytokine storm in critical COVID-19 patients and a reduction in IL-6 levels by anti-inflammatory drugs is expected to ease CRS and reduce viral loads." (PMID 32973505, 2020). "In COVID-19 patients, serum IL-6 is increased significantly and correlates with respiratory failure, ARDS, and poor clinical outcomes." (PMID 32719672, 2020). "Reminiscent of the cytokine profiles of COVID-19 patients with severe disease, acute KD is characterized by high levels of IL-6, TNF-α, and TGF-β." (PMID 33244300, 2020). "IL-6 is a leading mediator influencing systemic inflammation and has shown increased concentrations among COVID-19 patients with ARDS." (PMID 33046113, 2020). "There were 2 additional COVID-19 patients who had IL-6 levels close to 1000 pg/mL as well as 4 patients whose IL-6 levels were above the level of detection for the assay." (PMID 32687484, 2020). "Patients suffering from severe coronavirus disease 2019 (COVID-19) show highly elevated levels of Gal-3, TNFα, IL-1β, and IL-6, as compared to those with moderate disease (De Biasiet al., 2020;Wanget al., 2020a)." (PMID 33082935, 2020). "Tocilizumab, a humanized monoclonal antibody, is able to bind both membrane bound receptors and soluble receptors for IL-6, and a potential drug for patients with severe COVID-19." (PMID 33364959, 2020). "ARDS was evident in severe complications experienced by COVID-19 patients in China admitted to intensive care units, where the specific involvement in reducing cytokines IL-1β and IL-6 production is a strategy for COVID-19 intervention." (PMID 33233560, 2020). "Most importantly, COVID-19 induces a cytokine storm and lymphopenia, with elevation of cytokine levels such as the IL-2 receptor, IL-6, IL-8, IL-10 and necrosis factor tumor-alpha (TNF α), explaining SARS and multi-organ failure." (PMID 33327546, 2020). "A moderate but significant elevation of IL-6 in the plasma of COVID-19-S patients might be an indicator of hypercytokinemia in lung and other organs, and intervention of the IL-6-mediated pathological cascade may reduce or alleviate the immune attack found in the lungs of COVID-19-S patients." (PMID 34676126, 2020). "Naringin also inhibits the expression level of cyclooxygenase (COX)-2, inducible nitric oxide synthase (iNOS), IL-1β and IL-6 via suppressing high mobility group box 1 (HMGB1) in COVID-19." (PMID 33708124, 2020).
COVID-19 (continued). "The signatures of this common COVID-19 phenotype compared to influenza were equivalent levels of IL-6 and IL-8, paired with lower levels of cytokines in many other pathways and essentially the absence of any type I or type II IFN response." (PMID 33187979, 2020). "Increased circulating levels of IL-6 were also correlated with cardiac injury and mortality in COVID-19 patients." (PMID 33036180, 2020). "Tocilizumab is an interleukin-6 inhibitor that has shown promise in improving outcomes in patients with COVID-19." (PMID 32818119, 2020). "IL-6 together with other inflammatory biomarkers accompanied poor clinical and metabolic outcomes in COVID-19-infected patients." (PMID 33273888, 2020). "A multicenter, randomized controlled trial (ChiCTR2000029765) has been registered to evaluate the efficacy and safety of IL-6 blockade using tocilizumab in COVID-19." (PMID 32426374, 2020). "Our results are also in line with a recent meta-analysis showing raised WBC and lymphocytopenia in COVID-19 patients, and overproduction of cytokines, such as IL-6, correlating with disease severity." (PMID 32941548, 2020). "The expression levels of IL-6 represented almost 18-fold increase in COVID-19 patients compared to healthy controls (P-value<0.0001)." (PMID 33244382, 2020). "A preprint of this article (Treatment of ARDS and hyperinflammation in COVID-19 with IL-6 antagonist tocilizumab: a tertiary care experience from Pakistan) is available." (PMID 33510989, 2020). "Induction of pro-inflammatory cytokines (IL-1 and IL-6) and lung inflammation by COVID-19: anti-inflammatory strategies." (PMID 32256705, 2020). "Serum interleukin 6 (IL-6) is involved in the cytokine storm seen in COVID-19 patients who developed moderate to severe symptoms." (PMID 33362565, 2020). "Levels of IL-6 and IL-8 for COVID-19 patients were lower than for septic shock patients but comparable with those for OHCA and trauma patients." (PMID 33142828, 2020). "It is also known that in COVID-19 hyper-inflammatory condition, high level of IL-6 seem to be the main prognostic factor for worse outcomes." (PMID 32708322, 2020). "IL-6 is a potent proinflammatory cytokine and is a marker of the “cytokine storm” seen in patients with COVID-19." (PMID 32501751, 2020). "Peripheral blood IL-6 and leukocyte characteristics were retrospectively analyzed, to evaluate the correlation of these laboratory indicators with the severity of COVID-19." (PMID 33329518, 2020). "For example, interleukin 6 inhibitors are being tested in patients with COVID-19 (ClinicalTrials.gov Identifier: NCT04315298) but have been associated with intestinal perforation in IBD." (PMID 32513653, 2020). "Tocilizumab, an interleukin-6 monoclonal receptor antibody, has been used in some centers for mitigating the severe inflammatory response seen in patients with severe COVID-19 with encouraging results." (PMID 33456654, 2020). "Preliminary reports with retrospective and prospective cohorts describe the effects of blockade of IL-1, GM-CSFRα and IL-6 in COVID-19 patients." (PMID 32766256, 2020). "As the ∼1600 COVID-19 patients received IL-6/IL-6R blocking mAbs at the severe and critical stages, it is reasonable to expect that early treatment at stage 1 would have better outcomes." (PMID 32766256, 2020). "What's more, IL-6 is significantly increased in severe COVID-19 patients and plays a key role in the so-called “cytokine storm”." (PMID 33681238, 2020). "This study strongly suggests that IL-6 is a promising prognosis biomarker and therapeutic target in critically ill COVID-19 patients." (PMID 33072097, 2020). "IL-6 inhibitors, such as Tocilizumab, are currently being tried as a potential treatment for COVID-19 patients to reduce inflammation in the lungs and prevent progressive damage." (PMID 32708430, 2020). "While IL-6 was an available indicator in severe COVID-19 patients, IL-8 performed better in indicating the progress of COVID-19 disease status from mild to severe." (PMID 33488599, 2020).
COVID-19 (continued). "Such a reaction, known as a cytokine storm, involves the release of potentially overwhelming amounts of pro-inflammatory cytokines and chemokines into the blood stream of COVID-19 patients including, but not limited to, IL-6, TNF-α, INF-γ, CXCL9 and CXCL10." (PMID 32958009, 2020). "It should be noted that IL6 is responsible for the inflammatory storm that occurs in the most serious cases of patients with COVID-19." (PMID 32580440, 2020). "Patients with greater COVID-19 severity had a higher IL-6:AAT ratio, compared to patients who had community-acquired pneumonia." (PMID 33276468, 2020). "The inhibition of glucocorticoids to production of IL-6 certainly serves as a good predictive value for suppressing cytokine storm for COVID-19 patients at severe-to-critical stages." (PMID 32760915, 2020). "The overproduction of early response cytokines, such as tumor necrosis factor (TNF), interleukin-6 (IL-6) and interleukin-1β (IL-1β), has been described in patients severely affected by COVID-19." (PMID 33240326, 2020). "Research points to interleukin 6 (IL-6) as a crucial signature of the cytokine storm, and the clinical use of the IL-6 inhibitor tocilizumab shows potential for treatment of COVID-19 patient." (PMID 33584719, 2020). "ICU-COVID-19 patients had the highest concentrations of IL-1β, IL-6, IL-6 to IL-10 ratio, and tumor necrosis factor receptor superfamily member 1A (TNFR1)." (PMID 33142828, 2020). "When present at abnormally high levels, IL-6 in conjunction with soluble IL-6R compromises endothelial cells and the vasculature in experimental conditions (Section 4.3), and IL-6 peak levels mark disease severity in COVID-19." (PMID 32629875, 2020). "The increased plasma level of IL-6 and IL-1β in COVID-19 patients and the long-term effect of short period of elevated expression of these cytokines not yet completely known." (PMID 33352869, 2020). "The renin-angiotensin system, which controls blood pressure and electrolyte balance, is an additional important factor in IL-6 modulation and COVID-19 pathology." (PMID 33194450, 2020). "There are higher expression levels of proinflammatory cytokines including IL-2, IL-7, IL-6, G-CSF, IP-10, MCP-1, MIP-1A, and TNFα in severe COVID-19 patients, indicating that the cytokine storm was caused." (PMID 32719672, 2020). "First, the clinical efficacy of blocking IL-6 signaling in preventing mortality of COVID-19 patients is suboptimal." (PMID 32766256, 2020). "Th1 cells are notably proinflammatory and secrete cytokines such as IFN-γ, IL-1β, IL-2, and most pathologically in COVID-19, IL-6." (PMID 33510644, 2020). "Identifying biomarkers for these patients would potentially inform the utility of anti-IL-6 therapies in COVID-19." (PMID 33298930, 2020). "As cytokine storms played a critical role in the deterioration of COVID-19, we also detected the Th1/Th2 cytokines including IL-2, IL-4, IL-6, IL-10, TNF-α, and IFN-γ in patients infected with COVID-19." (PMID 33061829, 2020). "To find the possible reason of the hypercoagulability in cancer patients with COVID-19, we analyzed the association of coagulation indexes and platelet parameters with the levels of CRP, PCT, IL-6, lymphocytes and PaO2." (PMID 32766161, 2020). "Based on success in hematological and oncology settings, several IL-6 antagonists (tocilizumab, sarilumab as well as siltuximab) have been utilized as emergency interventions in COVID-19 patients with ARDS and hypotension, although so far with mixed results." (PMID 33013871, 2020). "Our primary goal was to directly compare levels of 6 inflammatory cytokines commonly associated with cytokine storm (IL-1β, IL-1RA, IL-6, IL-8, IL-18, and TNF-α) between severe COVID-19 patients and patients with ARDS or sepsis." (PMID 32706339, 2020). "We found that anti-IL-6 signaling agents significantly decreased mortality in patients with COVID-19." (PMID 33384605, 2020).